RNU6-862P (RNA, U6 small nuclear 862, pseudogene)
Gene: Small nuclear RNA gene on chromosome 17 (16,137,768 to 16,137,872, reverse strand). Ensembl gene ENSG00000199674.
Homologues: Orthologues: chimpanzee U6 (99% identical), macaque U6 (97% identical), rat LOC120093917 (72% identical), mouse Gm23819 (70% identical). Paralogues in human: RNU6-11P (92% identical), RNU6-37P (92% identical), RNU6-116P (91% identical), RNU6-33P (91% identical), RNU6-1 (90% identical), RNU6-1251P (90% identical), RNU6-140P (90% identical), RNU6-15P (90% identical), RNU6-199P (90% identical), RNU6-2 (90% identical), RNU6-25P (90% identical), RNU6-3P (90% identical), and 1287 more.